DICER1 (dicer 1, ribonuclease III)
Diseases named in the same sentence as DICER1 in open-access papers (continued):
Sharing a sentence is not in itself a finding about the gene and the disease.
tumor (continued). "To better understand the neoplasia phenotype associated with DICER1 variation, we now quantify the frequency of DICER1 variation in cancer populations." (PMID 30672147, 2019). "The DICER1 FTPS increases the risk for multiple tumor types, and the presence of any such tumors, and certainly the presence of more than one such tumor, should trigger investigation for a germline DICER1 mutation." (PMID 31349569, 2019). "We validated a germinal truncating mutation in DICER1, which was consistent with a DICER1 Syndrome diagnosis, providing the first example of an ovarian fibrosarcoma as the presenting neoplasia in this syndrome." (PMID 29459759, 2018). "Loss of function germline mutations in one allele of DICER1 was found to be common among patients, and the RNase IIIb hotspot mutations were less common, but more frequently found within the tumor." (PMID 29762508, 2018). "A further study used human tumour data from The Cancer Genome Atlas to profile the effects of DICER1 mutations on the miRNA profiles of the patients." (PMID 30306785, 2018). "Loss of Dicer1-induced abnormal expression of the miRNA let-7 family, which comprises well-known tumor suppressors, thus regulating stemness in EC cells." (PMID 29596364, 2018). "The emphasis remains on improving the care for patients who carry DICER1, in particular, screening for tumours that are linked to the mutation." (PMID 30306785, 2018). "The role of lncRNAs in neoplasias associated with DICER1 alterations need to be studied in more detail." (PMID 29459759, 2018). "Sertoli-Leydig cell tumours of the ovary (SLCT) are rare tumours predominantly caused by mutations in the DICER1 gene." (PMID 30356399, 2018). "Of particular interest, a bi-allelic Dicer1 mutation conferring a glycine substitution at position 1804 and 1807 was observed in one single mouse tumor." (PMID 29492199, 2018). "In one Th-MYCN driven tumor, a bi-allelic Dicer1 missense mutation known to affect the activity of the RNAse III domain was observed, reducing 5p end processing of pre-miRs including reduced levels of miRNAs of the let-7 family." (PMID 29492199, 2018). "The presence of somatic DICER1 mutation and further alterations in driver genes was investigated in genomic DNA obtained from available tumor samples." (PMID 28222777, 2017). "Mutations in DICER1 lead to an abnormally short Dicer protein that is unable to aid in the production of miRNA; Dicer acts as an oncogene or tumor suppressor in varying contexts, including varied roles in bladder cancer." (PMID 28589857, 2017). "Point mutations in DICER1 have also been described leading to tumor predisposition and referred to as DICER1 syndrome." (PMID 26990999, 2016). "Here, we showed that a weak DICER1 expression was associated with larger tumor size, more advanced staging and higher Weiss score." (PMID 26087193, 2015). "Germline mutations in DICER1 were identified in the rare familial pleuropulmonary blastoma–family tumor and dysplasia syndrome." (PMID 25676695, 2015). "In mouse models of cancer, the loss of a single Dicer1 allele (haploinsufficiency) reduced the time to tumor onset or survival time." (PMID 26087193, 2015). "A small 2014 case-series found DICER1 mutations in 6 NCMH patients, establishing a link to the DICER1 tumour spectrum." (PMID 26138824, 2015). "The recent findings are consistent with the observations that certain families of miRNAs are indispensable for tumor cell development that is why the inactivation of both DICER1 alleles suppresses cancer." (PMID 25883138, 2015). "Dicer1 is a haploinsufficient tumour suppressor in human cancer and loss of one Dicer1 allele is sufficient for the formation of tumours in breast, kidney, stomach, intestine, liver, lungs and pancreas." (PMID 25052766, 2014). "It has been reported that the abundance of DICER1, the enzyme that catalyzes the final step of miRNA maturation, is directly associated with tumor progression." (PMID 23667495, 2013).
tumor (continued). "The expression levels of PTEN, a known tumor suppressor gene in the colon, were also dependent on the number of intact Dicer1 alleles in both tumors and non-tumor tissues." (PMID 24023722, 2013). "Determining how altered DICER1 expression and or DICER1 mutations impact miRNA expression and function as tumor suppressors will be important for assessing how best this insight can be used to develop therapeutic targets and biomarkers." (PMID 23641362, 2013). "The expression levels of DICER protein in tumors were approximately proportional to the number of remaining wild-type Dicer1 alleles and similar to those in the non-tumor colonic epithelial cells." (PMID 24023722, 2013). "EMT is a crucial event in tumor progression, and it is associated with dysregulation of DICER1, E-cadherin and miR-200 family, and upregulation of vimentin, N-cadherin, Twist1, Snail and Zeb2." (PMID 23680357, 2013). "Additional analysis of other tumour types identified a somatic DICER1 hotspot mutation in one of 14 TGCT samples, raising the possibility of mutations within this domain of DICER1 also playing a role in TGCT development." (PMID 23068969, 2012). "Rather, their diagnostic significance lies in the integration of molecular findings with lesion type, cytomorphology, histology, patient age, and clinical context, including the selective recognition of cases in which constitutional DICER1-related tumor predisposition should be considered." (PMID 42207300, 2026). "DICER1-mutated thyroid lesions can range from indolent to aggressive neoplasms." (PMID 41556091, 2026). "Although patients with germline and mosaic DICER1 mutations are at risk for metachronous, bilateral SLCTs, predisposing DICER1 mutations have been associated with improved recurrence-free and overall survival compared to tumor-limited mutations." (PMID 41416308, 2025). "Larger documentations are needed to determine whether oncocytic changes are indeed more frequent in DICER1‐mutated neoplasms and to clarify the underlying molecular mechanisms." (PMID 41104964, 2025). "The rarity of this presentation in the nasal fossa at this age, coupled with its implications for diagnosis, treatment, and familial screening, emphasizes the need for awareness of the morphology patterns of DICER1-associated neoplasms across diverse anatomical sites." (PMID 41335141, 2025). "DICER1 P/LPVs are over-represented in follicular variant tumours." (PMID 40361475, 2025). "RNase IIIb-mutated DICER1 exhibits abnormal 5p microRNA processing, resulting in an altered 5p:3p microRNA ratio, which, together with simultaneous dysregulation of gene expression, underlies tumor development." (PMID 40892116, 2025). "The initial DICER1 genetic mutation can then be linked to a secondary genetic mutation, which can be either another somatic genetic mutation, a “mosaic landscape”, or a distinct germline genetic mutation to facilitate tumor development." (PMID 39857323, 2025). "Although the time interval in these very young infants that may be open to permit early tumor detection is small, it is an important consideration in index families where the DICER1 germline mutation may be known from birth." (PMID 40361440, 2025). "For example, DICER1 syndrome may be revealed, which is a genetic tumor syndrome caused by a mutation in the DICER1 tumor suppressor gene." (PMID 39963649, 2025). "We then assessed the consequences of Dicer1 loss on tumor growth and differentiation." (PMID 41002430, 2025). "CBME is among the spectrum of neoplasms associated with DICER1 cancer predisposition syndrome." (PMID 40150037, 2025). "Notably, the presence of cartilage foci within a RMS-like neoplasm represents a strong clue to an underlining DICER1 alteration." (PMID 41335141, 2025).
tumor (continued). "Data from the International Ovarian and Testicular Stromal Tumor (OTST) Registry suggest that such tumors present at a younger age in patients with predisposing germline or mosaic DICER1 mutations compared to those with tumor-limited mutations (16 versus 21 years)." (PMID 41416308, 2025). "Evaluation of DICER1 mutations could be beneficial in cases of more aggressive tumours occurring at younger ages, since DICER1 mutations are associated with early-onset follicular-patterned neoplasms and PDTC." (PMID 41104964, 2025). "Our literature review demonstrates that within the 248 cases, which include three intracranial DICER1-mutated neoplasias and one reference group, most somatic mutations accumulate in the RNase IIIb domain, while germline mutations are usually evenly distributed throughout the gene." (PMID 40361440, 2025). "To do so, we selectively inactivated one (Dicer1+/−) or both (Dicer1−/−) alleles specifically in thyroid follicular cells of two-month-old mice, a time point at which tumor initiation has already occurred and the model recapitulates key molecular and histopathological features of the human disease." (PMID 41002430, 2025). "More studies about environmental exposures and their role in tumor formation could aid in creating a better model to predict cancer risk in DICER1 patients." (PMID 40940982, 2025). "It is often observed that this tumor presents with DICER1 hotspot mutations." (PMID 40007992, 2025). "In addition to the constitutional DICER1 p.(Tyr1357fs*18) variant, the somatic DICER1 p.(Asp1910Tyr) oncogenic variant was also identified in this tumor." (PMID 40892116, 2025). "In addition, a somatic second-hit DICER1 variant affecting the RNase IIIb domain was found in a tumor following comprehensive molecular testing." (PMID 38415346, 2024). "A second somatic variant in DICER1 was, however, found in the tumor." (PMID 39037077, 2024). "Thus, a DICER1-associated highly malignant spindle-cell sarcoma with rapid tumor growth was diagnosed." (PMID 38976022, 2024). "Finally, a new tumor type has been introduced: the “blastoma of the hypophysis,” associated with DICER1 mutations." (PMID 39135755, 2024). "Moreover, DICER1-mut DTC typically lack other tumor-initiating driver mutations, suggesting that DICER1 mutations are the sole drivers of these tumors." (PMID 36896180, 2023). "Whether a missense variant as in patient 2 is sufficient to lead to tumor development or a second somatic hit in DICER1 is needed, as presumed in patients with LOF variants, remains speculative." (PMID 34331184, 2023). "Primary intracranial sarcomas, DICER1-mutant present a high level of tumor mutational burden." (PMID 36737790, 2023). "While DICER1-associated mesenchymal tumor classes may share similar cellular backgrounds, other DICER1-associated neoplasms likely have different cellular origins depending on the tumor location." (PMID 36966138, 2023). "With few exceptions, both benign and malignant DICER1-driven neoplasms follow a distinct modified two-hit hypothesis: one loss of function variant plus one variant selectively impairing the RNase IIIb domain function." (PMID 38084291, 2023). "Tumour tissue sequencing usually detects biallelic, compound pathogenic variants of DICER1, while a second pathogenic variant is probably acquired during tumourigenesis, consistent with Knudson’s two-hit hypothesis." (PMID 37626640, 2023). "Accurate variant curation and classification are essential for reliable diagnosis of DICER1-related tumor predisposition and the identification of individuals who may benefit from surveillance." (PMID 38084291, 2023). "It has been shown that DICER1 deficiency leads to miRNA dysfunction and promotes tumor progression." (PMID 37495108, 2023). "Characterization of DNA methylation associated proteins, as well as chromatin structure and composition may allow a better understanding on how DNA hypomethylation may be induced in DICER1-associated neoplasms." (PMID 36966138, 2023).
tumor (continued). "Reduced expression of Dicer1 is known to be associated with various cancers, and miRNAs may exert oncogenic or tumor-suppressing functions under certain conditions." (PMID 35736213, 2022). "Next, WES was performed in surgical formalin-fixed paraffin-embedded (FFPE) tumor tissues and paired normal control (peripheral blood) in order to determine whether this patient harbored somatic DICER1 mutation and other genetic variants." (PMID 36153506, 2022). "Despite the disparate primary sites of the DICER1-associated neoplasms, many of these tumors have overlapping pathologic features to possibly reflect their origin in sites of branching morphogenesis (lung, kidney, liver), a key developmental role of DICER119,20." (PMID 34599283, 2022). "When these tumors occur in those with germline DICER1 mutations, there is commonly loss of heterozygosity of the wild-type DICER1 allele which is contrary to the other DICER1-associated neoplasms in which the “second-hits” are somatic missense RNase IIIb hotspot mutations." (PMID 34599283, 2022). "These pathologic findings in the appropriate clinical setting should serve to alert the pathologist to the possibility of a DICER1-associated neoplasm and initiate appropriate testing on the neoplasm and to alert the clinician about the concern for a DICER1 mutation." (PMID 34599283, 2022). "Interestingly, the types of tumours which develop due to DICER1 hotspot mutations are unevenly distributed among the targeted tissues." (PMID 33208384, 2022). "Moreover, data is accumulating that DICER1 can function as a haploinsufficient tumor suppressor, in which a single mutational event would suffice for tumor development." (PMID 32712880, 2021). "However, the relationship between Dicer1 and tumor invasion and migration and their underlying mechanisms are unclear." (PMID 33763118, 2021). "CTL-derived IFN-γ amplified M1 polarization of DICER1-deficient TAMs and inhibited tumor growth." (PMID 34199293, 2021). "However, also sporadic DICER1-associated neoplasms with biallelic DICER1 alterations have been identified in the absence of germline alterations." (PMID 33846547, 2021). "DICER1 pathogenic variant carriers who have experienced a tumor may require additional surveillance of the organ that was affected." (PMID 34170462, 2021). "In addition, other interesting genetic mutations identified in tumor tissue at the time of pazopanib resistance included DICER1." (PMID 32957974, 2020). "In addition, specific somatic mutations in the DICER1 RNase III catalytic domain have been identified in several DICER1-associated tumor types." (PMID 33574795, 2020). "Notably, many of these DICER1-associated neoplasms have some site dependent morphological resemblance to the developmental stages in organogenesis, resulting into a teratoid or blastomatous appearance in many of them." (PMID 32507920, 2020). "An excellent review of the increased urogenital tumor-specific risks associated with germline DICER1 mutations has recently been published, and reviews the incidence and associations in greater detail; a more general review of all associated tumor types is also available." (PMID 31349569, 2019). "Interestingly, our cross-cancer analyses reveal DICER1 RNase IIIa/b hotspot mutations in restricted tumor types." (PMID 31417090, 2019). "These few include known tumor suppressors such as the let-7 and miR-15/16 families, both of which comprise 5p mature miRNA species whose defective biogenesis is a direct consequence of biallelic RNase IIIa/b hotspot mutations in DICER1." (PMID 31417090, 2019). "Loss of DICER1 is linked to multiple tumours, with prominent endocrine representation." (PMID 30306785, 2018). "The two-hit hypothesis applies to DICER1 mutations and the role of Dicer as a tumor suppressor gene." (PMID 29762508, 2018).
tumor (continued). "The haploinsufficiency mechanism proposed for DICER1 postulates that the constitutional mutation inactivating one allele of DICER1 (a heterozygous germline mutation), is initiatory and predisposes a cell to neoplastic disease; however, some other events are also required to induce tumorigenesis." (PMID 25883138, 2015). "We hypothesized that loss of DICER1 function in lung epithelium leads to persistent overgrowth of mesenchyme (and subsequent risk for malignancy), implicating an indirect tumor initiation mechanism." (PMID 25978641, 2015). "To date, 45 different pathogenic germ-line DICER1 mutations have been reported in 53 probands with various neoplasms worldwide, including frameshift, nonsense, splicing and missense mutations scattered throughout the gene, as well as large genomic rearrangements." (PMID 24708902, 2014). "In human neoplasias, CpG island hypermethylation is associated with transcriptional silencing of tumor suppressor genes including genes that encode miRNAs, which are produced by DICER1, a cytoplasmic RNase III enzyme." (PMID 23680357, 2013). "Identification of neoplasia-associated germ-line and somatic mutations in DICER1 indicates that mis-expression of miRNAs in cancer may result from defects in their processing." (PMID 23547758, 2013). "Frequent loss of one allele of Dicer1 has been observed in several different tumor types causing a global reduction of steady-state micro RNA levels that could be functionally suppressive to the oncogenesis and metastasis of CUP." (PMID 23671674, 2013). "Evidence from previous studies suggest Dicer1 functions as a context-dependent haplo-insufficient tumor suppressor gene: partial loss may promote tumor development, whereas complete loss may disrupt essential cellular functions, causing cell death and tumor suppression." (PMID 41002430, 2025). "However, the mechanisms of tumor progression in DICER1-associated tumors may be driven by gene expression variations without alteration in the DNA sequence." (PMID 40448797, 2025). "Up to 10% of female patients with DICER1 tumor predisposition may develop sex cord-stromal tumors and approximately 50% of patients with Sertoli-Leydig tumors and gynandroblastomas have a pathogenic germline DICER1 variant." (PMID 40100464, 2025). "Consequently, considering the potential clinical benefit, it might be worthwhile to screen patients with identified DICER1 variants in tumor tissue for constitutional involvement." (PMID 38252873, 2024). "Indeed, the prognosis of the tumor is closely related to the tumor stage, the degree of differentiation, the mitotic count, the presence of a retiform pattern and heterologous elements, the presence of the DICER1 variant, and the quality of the surgery." (PMID 38136408, 2023). "Furthermore, we have recently shown that both ERMS with DICER1 PVs and a tumor entity termed “primary intracranial sarcoma, DICER1-mutant” (PIS DICER1) are associated with DNA methylation signatures that are distinct from their morphological counterparts that are not DICER1-associated." (PMID 36966138, 2023). "DICER1-related tumor predisposition therefore represents an unusual form of Knudson’s two-hit hypothesis, since the somatic mutation affects the ability of DICER1 RNase IIIb domain to process 5p miRNAs, while keeping its capacity to generate 3p miRNAs by the preserved RNase IIIa domain." (PMID 36896180, 2023). "We demonstrate that DICER1 pathogenic somatic mutations were associated with a global reduction of 5p-derived miRNAs, including those particularly abundant in the non-neoplastic thyroid tissue such as let-7 and mir-30 families, known for their tumor suppressor function." (PMID 36896180, 2023).